LGALS14 (galectin 14)
Description:
Binds beta-galactoside and lactose. Strong inducer of T-cell apoptosis.
Synonyms: CLC2; PPL13
Tractability: No criterion of Open Targets' tractability assessment is met for any kind of drug.
Gene: Protein-coding gene on chromosome 19 (39,704,481 to 39,709,444, forward strand). Ensembl gene ENSG00000006659.
Subcellular location: Nucleus
Subcellular location (Human Protein Atlas): Nucleoplasm
Gene Ontology:
Molecular function: protein binding; carbohydrate binding
Cellular component: nucleoplasm; nucleus
Genetic constraint (gnomAD): Loss-of-function variants: 13 observed, 12.74 expected, observed/expected ratio (o/e) 1.02, 90% interval 0.66 to 1.61. The upper end of that interval is the gene's LOEUF score, 1.61, which puts it in group 6 of 6, group 1 being the genes least tolerant of losing a copy. Missense variants: 154 observed, 147.87 expected, observed/expected ratio (o/e) 1.04, 90% interval 0.91 to 1.19. Synonymous variants: 49 observed, 55.07 expected, observed/expected ratio (o/e) 0.89, 90% interval 0.71 to 1.13.
Homologues: Orthologues: macaque LGALS14 (53% identical), Caenorhabditis elegans lec-1 (32% identical), Caenorhabditis elegans lec-3 (30% identical), zebrafish lgals3b (29% identical), Caenorhabditis elegans lec-12 (25% identical), mouse Lgals9 (25% identical), rat Lgals5 (25% identical), rat Lgals9 (25% identical), tropical clawed frog lgals9 (25% identical), tropical clawed frog lgals9 (24% identical), zebrafish lgals9l6 (24% identical), zebrafish si:dkey-95h12.2 (24% identical), and 23 more. Paralogues in human: LGALS13 (68% identical), LGALS16 (61% identical), CLC (50% identical), LGALS4 (29% identical), LGALS3 (28% identical), LGALS7 (27% identical), LGALS7B (27% identical), LGALS8 (27% identical), LGALS9B (24% identical), LGALS9C (24% identical), LGALS9 (24% identical), GRIFIN (19% identical), and 4 more.
Diseases named in the same sentence as LGALS14 in open-access papers:
LGALS14 is named in the same sentence as 14 diseases in open-access papers, as found by Europe PMC text mining. Sharing a sentence is not in itself a finding about the gene and the disease. The quoted sentences say what the papers report.
preeclampsia (6 papers, 2018 to 2023). Preeclampsia is a hypertensive disorder of pregnancy that is characterized by new-onset hypertension with proteinuria presenting after 20 weeks of gestation, and depending on mild or severe forms may initially present with severe headache, visual disturbances, and hyperreflexia. "The dysregulation of galectin-14 is involved in the pathogenesis of early pregnancy loss and preeclampsia." (PMID 33796532, 2021). "Galectin-14 was significantly decreased in the villi of early pregnancy loss and the placenta of preeclampsia." (PMID 33796532, 2021). "The dysregulation of placental galectin-14 in early pregnancy loss and preeclampsia implies its possible role in the pathogenesis of pregnancy complications and in the regulation of trophoblasts." (PMID 33796532, 2021). "In the current study, the placental expressions of galectin-14 in early pregnancy loss and severe preeclampsia were determined, the effects of galectin-14 on the migration and invasion of trophoblast were observed, and mechanisms behind were explored." (PMID 33796532, 2021). "Placental expression of galectin-14 was significantly lower in both early pregnancy loss and preeclampsia as compared with their controls." (PMID 33796532, 2021). "An in vivo research will enhance our insight into the roles of galectin-14 in pregnancy, placental development, and pathogeneses of early pregnancy loss and preeclampsia." (PMID 33796532, 2021). "In the current investigation, we found the decreased placental expression pattern of galectin-14 in early pregnancy loss and preeclampsia, which were consistent with previous studies." (PMID 33796532, 2021). "The extravillous trophoblast from the cervix of early pregnancy loss patients had a reduced level of galectin-14; also, downregulation of galectin-14 has been found in preterm severe preeclampsia." (PMID 29950926, 2018). "Thus, the dysregulation of galectin-14 in trophoblasts is involved in the pathogenesis of early pregnancy loss and preeclampsia." (PMID 33796532, 2021). "Predominantly placenta-expressed genes, down-regulated in module M1, are regulators of fetal growth (CSH1, HSD11B2), metabolism (ESRRG), estrogen synthesis (HSD17B1), and immune functions (LGALS14), some of which were reported to be down-regulated in preeclampsia." (PMID 30135684, 2018).
ovarian carcinoma (4 papers, 2021 to 2023). A malignant neoplasm originating from the surface ovarian epithelium. "More recently, our research team has used in silico and in vitro approaches to show that high expression of LGALS14, the gene encoding GAL-14, is associated with shorter survival in ovarian cancer cells." (PMID 36766779, 2023). "Through in vitro studies of ovarian cancer cell lines, we further confirmed that LGALS14 is readily expressed in HGSA." (PMID 36766779, 2023). "Galectin-14 is expressed at a high level in several cancer types, including liver, breast, uterine, and ovarian cancer." (PMID 36873388, 2023). "Furthermore, increased expression of galectin-14 has been reported to correlate with shorter survival in high-grade serous adenocarcinoma ovarian cancer." (PMID 36873388, 2023). "We also found that LGALS14 is preferentially expressed in high-grade serous adenocarcinoma (HGSA), the most aggressive subtype of ovarian cancer." (PMID 36766779, 2023).
Miscarriage (3 papers, 2019 to 2025). A pregnancy that ends at a stage in which the fetus is incapable of surviving on its own, defined as the spontaneous loss of a fetus before the 22th week of pregnancy. "Such research is limited for placental galectins and has not yet been performed for gal-1, therefore, further studies are warranted to explore the association of LGALS1, LGALS13, LGALS14, and LGALS16 polymorphism with miscarriage, PE, or IUGR." (PMID 40839117, 2025).
liver cancer (1 paper, 2023). An epithelial or non-epithelial malignant neoplasm that arises from the liver. "The aberrant expression of galectin-14 was significantly associated with a poor overall survival of liver cancer patients with database analysis." (PMID 37977559, 2023).
lung carcinoma (1 paper, 2023). "One of the most striking findings was that almost 75% of lung cancer patients expressed LGALS14." (PMID 36766779, 2023).
nematode infection (1 paper, 2018). "Hence, the expression of genes such as ITLN2, CLCA1, galectin 14, etc. appear to be consistently affected by nematode infection, in both lambs and adult sheep." (PMID 29703268, 2018).
parasitic infection (1 paper, 2018). "The involvement of ruminant-specific galectin-11 (LGALS-11) and galectin-14 (LGALS-14) has been postulated to play important roles in protective immune responses against parasitic infection; however, their ligands are unknown." (PMID 29576976, 2018).
infection (5 papers, 2011 to 2025). The state of being infected such as from the introduction of a foreign agent such as serum, vaccine, antigenic substance or organism. "Galectin-14 is constitutively expressed in eosinophils and is secreted following a stimulus, whereas galectin-11 is specifically up-regulated following infection." (PMID 41008542, 2025). "Additionally, through transcriptional studies, galectin-14 has been shown to be up-regulated in peripheral mononuclear bone marrow cells at 2 and 8 weeks post-infection and in the liver tissue of infected animals." (PMID 41008542, 2025). "Due to the lack of convincing natural resistance in any species to F. hepatica and the recruitment of eosinophils to the site of infection, it has been speculated that flukes could be manipulating host galectin-14 and eosinophils for their survival." (PMID 41008542, 2025). "In addition, the number of eosinophils and galectin-14 transcripts in the skin, and the cytokine levels in skin-LN cultures, was greater in the high-dose animal at 11–12 DPI than at 5–6 DPI, whereas the inverse was true for each of the buffaloes receiving a moderate challenge infection." (PMID 24086786, 2013).
tumor (3 papers, 2016 to 2025). "By doing this, we found that galectin-14 might be a potential molecule associated with HCC tumor growth." (PMID 37977559, 2023). "Theoretically, targeting galectin-14 in HCC would only have a minor off-tumor effect because galectin-14 was only expressed in adult placenta." (PMID 37977559, 2023). "In the current study, we performed a single cell-clone-based screening and identified galectin-14 as an essential molecule in the regulation of tumor growth." (PMID 37977559, 2023). "Galectin-14 promoted HCC cell proliferation by increasing the expression level of cell surface HSPGs to sensitize tumor cells responding to growth factors." (PMID 37977559, 2023). "Knocking down galectin-14 inhibited the proliferation of tumor growth, whereas overexpressing galectin-14 promoted tumor growthin vivo." (PMID 37977559, 2023). "With these considerations, we obtained single Huh-7 cell clones, compared their tumor growth ratein vitro andin vivo, selected those clones with significantly different growth rates to perform RNA-seq analysis, and finally identified galectin-14 as a candidate molecule regulating HCC tumor growth." (PMID 37977559, 2023). "Altogether, these results suggest that galectin-14 may play important roles in tumor progression and has the potential to be a therapeutic target for HCC." (PMID 37977559, 2023). "Such ideal tumor specificity may make galectin-14 a good biomarker or therapeutic target." (PMID 37977559, 2023). "In the current study, we identified a novel onco-fetal molecule galectin-14 in HCC by a single cell clone-based screening, and demonstrated that galectin-14 could increase the expression of HSPGs, causing tumor cells sensitize to growth factor and consequently promoting HCC tumor growth." (PMID 37977559, 2023). "However, we found that 20% of our collected HCC tumor tissue samples expressed galectin-14." (PMID 37977559, 2023). "Therefore, we could further design a new strategy to intervene in the expression of galectin-14 to attenuate HCC tumor growth." (PMID 37977559, 2023). "The anti-tumor effects of galectin-14 against HCC have not yet been evaluated." (PMID 27494117, 2016).
LGALS14 also shares sentences with these, for which no sentence is quoted: cancer (2 papers); hepatocellular carcinoma (2); Allergy (1); cervical cancer (1); skin infection (1).